GRM4 (glutamate metabotropic receptor 4)
Description:
G protein-coupled receptor for glutamate. Ligand binding causes a conformation change that triggers signaling via guanine nucleotide-binding proteins (G proteins) and modulates the activity of down-stream effectors. Signaling inhibits adenylate cyclase activity.
Synonyms: mGluR4; GPRC1D; mGlu4
Tractability: Small molecule: a drug acting on it is in phase 2 or 3 trials; a structure with a bound ligand is known; a high-quality ligand is known; it belongs to a druggable protein family. Antibody: UniProt places it where antibodies can reach, with high confidence; its Gene Ontology location is reachable by antibodies, with high confidence; UniProt predicts a signal peptide or a membrane-spanning region. PROTAC: a small molecule that binds it is known.
Target class: Family C G protein-coupled receptor; Metabotropic glutamate receptor; Small molecule receptor (family C GPCR); Membrane receptor; Neurotransmitter receptor (family C GPCR)
Chemical probes: CHEMBL1830711, CHEMBL3609742, VU 0364770, VU 0422288, VU0155094, VU0361737, VU0400195
Gene: Protein-coding gene on chromosome 6 (34,018,643 to 34,155,622, reverse strand). Ensembl gene ENSG00000124493.
Subcellular location: Cell membrane
Pathways (Reactome):
Signal Transduction: Class C/3 (Metabotropic glutamate/pheromone receptors); G alpha (i) signalling events
Sensory Perception: Sensory perception of sweet, bitter, and umami (glutamate) taste
Gene Ontology:
Molecular function: G protein-coupled receptor activity; glutamate receptor activity; adenylate cyclase inhibiting G protein-coupled glutamate receptor activity
Biological process: adenylate cyclase-inhibiting G protein-coupled glutamate receptor signaling pathway; G protein-coupled glutamate receptor signaling pathway; positive regulation of MAPK cascade; chemical synaptic transmission; neurotransmitter secretion; regulation of neuron apoptotic process; regulation of synaptic transmission, glutamatergic; G protein-coupled receptor signaling pathway
Cellular component: cytoplasmic vesicle; plasma membrane; membrane; presynapse; synapse
Genetic constraint (gnomAD): Loss-of-function variants: 27 observed, 77.05 expected, observed/expected ratio (o/e) 0.35, 90% interval 0.26 to 0.48. The upper end of that interval is the gene's LOEUF score, 0.48, which puts it in group 2 of 6, group 1 being the genes least tolerant of losing a copy. Missense variants: 936 observed, 1,321.7 expected, observed/expected ratio (o/e) 0.71, 90% interval 0.67 to 0.75. Synonymous variants: 486 observed, 543.53 expected, observed/expected ratio (o/e) 0.89, 90% interval 0.83 to 0.96.
Homologues: Orthologues: chimpanzee GRM4 (99% identical), macaque GRM4 (99% identical), dog GRM4 (98% identical), rabbit GRM4 (98% identical), pig GRM4 (98% identical), mouse Grm4 (97% identical), rat Grm4 (96% identical), guinea pig GRM4 (96% identical), tropical clawed frog grm4 (79% identical), zebrafish grm4 (79% identical), Drosophila melanogaster mGluR (45% identical). Paralogues in human: GRM8 (74% identical), GRM7 (68% identical), GRM6 (66% identical), GRM2 (44% identical), GRM3 (43% identical), GRM5 (41% identical), GRM1 (41% identical).
Diseases named in the same sentence as GRM4 in open-access papers:
GRM4 is named in the same sentence as 74 diseases in open-access papers, as found by Europe PMC text mining. Sharing a sentence is not in itself a finding about the gene and the disease. The quoted sentences say what the papers report.
osteosarcoma (17 papers, 2013 to 2024). A usually aggressive malignant bone-forming mesenchymal neoplasm, predominantly affecting adolescents and young adults. "On the other hand, for risk factors, research has shown that GRM4 high expression is linked with higher mortality in osteosarcoma patients." (PMID 38586328, 2024). "Using an irradiation-induced osteosarcoma model, we found that Grm4-/- mice were more susceptible to developing tumors compared with WT mice, and treatment with an agonist of mGluR4 efficiently suppressed osteosarcoma progression." (PMID 36817470, 2023). "Several previous studies suggested that GRM4 gene polymorphism was associated with susceptibility and prognosis of osteosarcoma in human." (PMID 31306098, 2019). "A genome-wide association study (GWAS) in humans identified two loci associated with the presence of osteosarcoma in a gene desert of chromosome 2, specifically in the glutamate receptor metabotropic 4 (GRM4) gene." (PMID 31130627, 2019). "Osteosarcoma patients with higher GRM4 were associated with poorer EFS and OS." (PMID 36305631, 2022). "Previous genome-wide association studies identified two susceptibility loci for osteosarcoma, one of which that achieved genome-wide significance was a single nucleotide intronic variant, rs1906953, at 6p21.3, in the glutamate receptor metabotropic 4 (GRM4) gene." (PMID 37228489, 2023). "Although not formally and biochemically confirmed, it is believed that rs1906953, which is located at a DNase I hypersensitive site, enhances transcription of GRM4 given that it is overexpressed in the majority of osteosarcomas." (PMID 37228489, 2023). "GRM4 is involved in the metastasis of osteosarcoma and affects the survival of osteosarcoma patients." (PMID 28678795, 2017). "The human OS GWAS compared 941 patients with osteosarcoma to 3,291 unaffected adults across 699,000 SNPs and found two genome-wide significant loci, one at the glutamate receptor gene GRM4 and the other in a gene desert." (PMID 24330828, 2013). "GRM4, a susceptibility gene for osteosarcoma, is expressed in osteocytes and neutrophil but not in tumour cells, and it was reported to selectively regulate IL23 and IL12 in myeloid cells, which promote osteosarcoma in mouse models." (PMID 36305631, 2022). "It has been proposed that CBX4 is retained in the cytoplasm through interaction with the glutamate metabotropic receptor 4 (GRM4), which then blocks nuclear CBX4‐mediated gene regulation, proliferation, migration, and invasion ability of osteosarcoma cells." (PMID 38426219, 2024).
depression (13 papers, 2018 to 2025). "L. rhamnosus HN001 did, however, affect the expression of genes in pathways associated with fear, anxiety and depression in the amygdala (Grm4) and produced minor changes in the microbiota, implicating actions on GBA pathways in the WKY strain." (PMID 37445611, 2023). "In humans, the amygdala links pain sensation with negative emotions, and activation of pathways associated with Grm4 has been found to reduce anxiety and depression where this is a symptom of persistent pain." (PMID 37445611, 2023). "miR-1202 is downregulated in patients with depression, and is associated with the GRM4 3′UTR region." (PMID 31010975, 2019). "In patients with depression, glutamate metabotropic receptor 4 (GRM4) expression increased, and miR-335 was significantly downregulated." (PMID 35562946, 2022). "Inducing depression in rat models was paired with downregulation of miR-29b-3p and increased levels of GRM4 in the prefrontal cortex, which were restored by ketamine administration." (PMID 35546951, 2022). "The miR-335 participates in treating severe depression by targeting glutamate metabotropic receptor 4 (GRM4)." (PMID 34419170, 2021). "Although there is no direct evidence that GRM4 modulates depression-like behaviors based on studies investigating GRM4-overexpressed or GRM4-knockdown animal models, GRM4 has been implicated in the regulation of MDD and is considered an attractive target for drug discovery." (PMID 30369596, 2018). "In our future research, we aim to further study the function of GRM4 in modulating depression-like behaviors and mediating the antidepressant effects of ketamine in GRM4-overexpressed or GRM4-knockdown animal models." (PMID 30369596, 2018). "Moreover, higher GRM4 protein expression has beforehand been reported to be incorporated with major depression and connectivity in brain activity." (PMID 32184864, 2019). "Therefore, GRM4 plays an important role in the downstream mechanism of miR-29b-3p in the progression of depression and ketamine’s antidepressant effects." (PMID 30369596, 2018). "In addition, relevant studies have shown that the increased expression of GRM4 is closely related to the occurrence and development of depression; hence, GRM4 may be involved in the pathogenesis of depression." (PMID 30369596, 2018). "The miR-29b-3p/GRM4 pathway acts as a critical mediator of ketamine’s antidepressant effect in depressive-like rats and could be considered a potential therapeutic target for treating major depression disorder." (PMID 30369596, 2018).
schizophrenia (11 papers, 2017 to 2025). A major psychotic disorder characterized by abnormalities in the perception or expression of reality. "GRM4 is a major excitatory neurotransmitter in central nervous system and it is a susceptible gene for bipolar disorder and schizophrenia." (PMID 31874630, 2019).
Anxiety (8 papers, 2015 to 2025). Intense feelings of nervousness, tension, or panic often arise in response to interpersonal stresses. "A particularly noteworthy observation common to these therapeutic interventions was the consistent upregulation of miR-335, previously shown to regulate glutamate metabotropic receptor 4 (GRM4), implicated with anxiety-associated behaviors." (PMID 38474112, 2024). "The increased expression of Grm4 in the amygdala is consistent with L. rhamnosus HN001 altering GABA–glutamate neurotransmitter-receptor pathways in brain regions associated with anxiety." (PMID 37445611, 2023). "GRM4 is related to the regulation of anxiety-related behaviors and can further regulate the expression of miR-335." (PMID 31010975, 2019).
colon cancer (7 papers, 2014 to 2025). "Although its expression correlates with poor prognosis in colorectal cancer and drug resistance in colon cancer, GRM4 agonists can inhibit the proliferation of non-CNS-origin cultured cancer cells, such as bladder cancer cells." (PMID 41573636, 2025).
breast carcinoma (6 papers, 2019 to 2025). "GRM4 emerges as a novel CAR-associated target for breast cancer, demonstrating tumor-specific overexpression, brain-restricted normal expression, and pan-subtype applicability with potential on-target off-tumor effect." (PMID 41573636, 2025). "Collectively, these findings establish GRM4 as a promising diagnostic marker in breast cancer." (PMID 41573636, 2025). "Here, we identified glutamate metabotropic receptor 4 (GRM4) as a novel target with dual advantages: breast cancer (BC)-predominant membrane expression and restricted normal tissue distribution, potentially circumventing on-target off-tumor toxicity." (PMID 41573636, 2025). "GRM4 not only serves as a target for CAR therapies in breast cancer but also can be used in the pathological diagnosis of breast cancer." (PMID 41573636, 2025). "In this study, we report the ectopic expression of GRM4 in breast cancer patients and indicated it is a potential target for CAR-associated therapy." (PMID 41573636, 2025). "GRM4 was expressed in luminal A, luminal B, triple-negative, Her-2(+)HR(+), and Her-2(+)HR (–) breast cancer, suggesting that GRM4 is broadly expressed in breast cancer." (PMID 41573636, 2025). "The expression of GRM4 in five distinct subtypes of breast cancer was characterized." (PMID 41573636, 2025). "In breast cancer, GRM4 inhibits the proliferation of breast cancer cell lines, yet its expression in clinical breast cancer samples remains unclear." (PMID 41573636, 2025). "The expression of GRM4 in later stage in breast cancer need exploration." (PMID 41573636, 2025). "Therefore, if GRM4-CAR-NK cells are to target breast cancer cells, the on-target off-tumor side-effect will be limited." (PMID 41573636, 2025). "Examination of breast cancer cell lines MDA-MB-231 and MCF7 for expression of GRM4, by WB and IF staining, in addition to IHC staining of 158 breast cancer specimens, showed that GRM4 is widely expressed in the cytoplasm and cell membrane of breast cancer cells." (PMID 41573636, 2025). "GRM4 is broadly expressed in breast cancer patients, suggesting GRM4 CAR-T therapy may exert a positive effect on almost 80% of patients." (PMID 41573636, 2025). "The exact biological role of GRM4 in breast cancer remains unclear and requires further investigation." (PMID 41573636, 2025). "GRM4 was the only GRM member that expressed in breast cancer tissues." (PMID 31492116, 2019). "Our results suggest that GRM4 might be a tumor suppressor gene in breast cancer under the direct regulation of miR-328-3p and miR-370-3p." (PMID 31492116, 2019). "Ectopic expression of GRM4 was correlated with better prognosis of breast cancer patients." (PMID 31492116, 2019). "Thus, GRM4 was preliminarily identified as a potential CAR-T therapy target for breast cancer." (PMID 41573636, 2025). "In our study, we found that in GRM4-positive patients, such as patients 4 to 9, GRM4 was expressed in the membrane and cytoplasm of breast cancer cells, while no GRM4 was expressed in normal breast tissues." (PMID 41573636, 2025). "This not only is supported by bio-informatic data in GEPIA database from TCGA patient cohort, but also analysis of our own clinical samples, indicating that GRM4 is not a decisive factor in the OS of breast cancer patients." (PMID 41573636, 2025). "In summary, regardless of the breast cancer subtype, GRM4 expression was at least 70% in any subtype, indicating its potential as a promising target for CAR-T therapy." (PMID 41573636, 2025). "As for breast cancer, GRM4 expression is not related to the OS." (PMID 41573636, 2025).
colorectal cancer (6 papers, 2014 to 2025). A primary or metastatic malignant neoplasm that affects the colon or rectum. "Some studies have illustrated that GRM4 correlates with poor prognosis in colorectal cancer." (PMID 41573636, 2025).
epilepsy (6 papers, 2017 to 2025). A brain disorder characterized by episodes of abnormally increased neuronal discharge resulting in transient episodes of sensory or motor neurological dysfunction, or psychic dysfunction. "De novo duplication in GRM4 gene was found in a patient with a severe psychomotor retardation, epilepsy, mild dysmorphic features and behavioral disturbances." (PMID 34273994, 2021).
glioblastoma (5 papers, 2018 to 2025). The most malignant astrocytic tumor (WHO grade IV). "Many of the identified differentially expressed genes are understudied in glioblastoma; however, several are key regulators of tissue remodeling (MFAP4 and ALX4), mesoderm development (TBX5 and ALX4), and immune modulation (FUT2, C4BPA, MFAP4, and GRM4)." (PMID 41066027, 2025).
autism (4 papers, 2016 to 2018). Persistent deficits in social interaction and communication and interaction as well as a markedly restricted repertoire of activity and interest as well as repetitive patterns of behavior. "In this context, several genes downregulated in the brainstem of Hoxa5 cKO mouse at P21, such as Grm4, Cbln1, En2, Camk4, and Cadps2, have been associated to autism traits either in humans or in mouse models." (PMID 29187810, 2017).
bipolar disorder (4 papers, 2014 to 2023). A disorder of the brain that causes unusual shifts in mood, energy, activity levels and the ability to carry out day-to-day tasks. "Meta-analyses and genome-wide association studies (GWAS), however, have found associations between Grm4 and several psychiatric disorders that share the impulsivity domain, such as PD, bipolar disorder, and ADHD." (PMID 34982027, 2022).
medulloblastoma (4 papers, 2017 to 2023). A malignant, invasive embryonal neoplasm arising from the cerebellum. "However, GRM4 can inhibit the proliferation and DNA synthesis of various medulloblastoma cell lines by inhibiting the cAMP and IP3K pathways." (PMID 33318294, 2020).
asthma (2 papers, 2019 to 2024). "In these studies, the GRM4 gene was the most frequent signal, where a higher number of variants with evidence of association with asthma susceptibility were located (min p = 5.29 × 10−9)." (PMID 30805318, 2019). "The GRM4 gene has been associated with several neurological disorders and different types of cancer but, it has not been associated with any asthma-related traits and it has not been implicated in any immune-related function." (PMID 30805318, 2019).
bone cancer (2 papers, 2013 to 2018). A primary or metastatic malignant neoplasm affecting the bone or articular cartilage. "Although glutamate signaling in primary bone cancers is not well understood, both GRM4 and GRIK4 are expressed in normal bone, and glutamate signaling has been shown to regulate bone formation and resorption." (PMID 24330828, 2013).
experimental autoimmune encephalomyelitis (2 papers, 2014 to 2024). An autoimmune demyelinating disease of the central nervous system that is produced experimentally in animals by the injection of homogenized brain or spinal cord in Freund's adjuvant. "In mouse experiments, it was found that knockout of GRM4 made mice highly susceptible to experimental autoimmune encephalomyelitis (EAE), a mouse model of multiple sclerosis." (PMID 39518863, 2024).
mood disorder (2 papers, 2025). A cognitive disorder a disturbance in which the person's mood is hypothesized to be the main underlying feature. "Additionally, L. rhamnosus significantly increased metabotropic glutamate receptor 4 (GRM4) expression, implicated in mood disorders for its role in modulating neurotransmitter release and post-synaptic glutamatergic signalling." (PMID 41497537, 2025).
behavior disorders (1 paper, 2020). "The pattern differences between sexes could be connected with differences in gene expression across sexes in multiple GRM genes including GRM4 in association with behavior disorders." (PMID 32848554, 2020).
cocaine addicts (1 paper, 2022). "Alcoholics and cocaine addicts show upregulation of three genes relative to controls: Gria4, Grik3, and Grm4." (PMID 36362437, 2022).
juvenile myoclonic epilepsy (1 paper, 2021). "The GRM4 gene variants were also described as associated with juvenile myoclonic epilepsy, characterized by myoclonic jerks, absence and generalized seizures." (PMID 34273994, 2021).
nematode infection (1 paper, 2019). "Two sub-units of NMDARS, NR2A and NR2B (also known as Grin2A and Grin2B) as well as several AMPARs including the metabotropic glutamate receptors 1 and 2 (mGlu-R1 and mGlu-R2), Gria3, Grm2, Grm4, Grik3 and Grik5 were up-regulated in the pup brain on P7 in response to maternal nematode infection." (PMID 30862816, 2019).
non-small cell lung carcinoma (1 paper, 2014). A group of at least three distinct histological types of lung cancer, including non-small cell squamous cell carcinoma, adenocarcinoma, and large cell carcinoma. "High-throughput genomic studies have identified GRM1, GRM3, GRM4, GRM8 and GRIN2A as susceptibility genes in non-small-cell lung cancer (NSCLC), melanoma, osteosarcoma, and bladder cancer." (PMID 25326682, 2014).
renal cell carcinoma (1 paper, 2020). "In renal cell carcinoma, GRM4 was previously found to be highly expressed and correlated with poor prognosis compared with that in normal samples." (PMID 33318294, 2020).